RBP4 (retinol binding protein 4)
Diseases named in the same sentence as RBP4 in open-access papers (continued):
Sharing a sentence is not in itself a finding about the gene and the disease.
preeclampsia (4 papers, 2018 to 2024). Preeclampsia is a hypertensive disorder of pregnancy that is characterized by new-onset hypertension with proteinuria presenting after 20 weeks of gestation, and depending on mild or severe forms may initially present with severe headache, visual disturbances, and hyperreflexia. "Nevertheless, the published documents about the association between RBP4 and the development of preeclampsia in humans are inconclusive." (PMID 36558360, 2022). "More longitudinal studies spanning the three trimester periods are needed to clarify the association of RBP4 and its dynamics in preeclampsia cases throughout pregnancy." (PMID 36558360, 2022). "Elevated RBP4 concentrations have been implicated in various pregnancy complications including preeclampsia, although the data remains controversial as there are inconsistencies noted between studies." (PMID 35405978, 2022). "This meta-analysis with high heterogeneity showed that higher levels of RBP4 were associated with preeclampsia risk." (PMID 36558360, 2022). "This systematic review and meta-analysis aimed to assess the association between RBP4 levels and preeclampsia." (PMID 36558360, 2022). "Retinol-binding protein 4 (RBP4) is claimed to be associated with the development of preeclampsia, yet the reports are inconclusive." (PMID 36558360, 2022). "From this paucity of studies, it is inconclusive whether first-trimester levels of RBP4 are associated with the development of preeclampsia." (PMID 36558360, 2022). "Therefore, we conducted this systematic review and meta-analysis to assess the association between RBP4 and preeclampsia." (PMID 36558360, 2022). "The PubMed, Google Scholar and ScienceDirect databases were searched for studies that investigated RBP4 levels in preeclampsia patients and compared them with normal controls." (PMID 36558360, 2022). "The major finding in this meta-analysis of 13 observational studies is that the RBP4 levels are higher in patients with preeclampsia compared with normal pregnant controls." (PMID 36558360, 2022). "It has been mentioned that RBP4 is significantly higher in cases that develop severe preeclampsia compared with mild cases." (PMID 36558360, 2022). "According to the random effect model, the SMD of RBP4 was significantly higher in women with preeclampsia compared with normal controls [SMD of RBP4: 0.55 ng/mL; 95% CI (0.06; 1.05); p = 0.028; I2 = 89%]." (PMID 36558360, 2022). "Taken together, all these premises have pointed to the involvement of RBP4 in the pathogenesis of preeclampsia." (PMID 36558360, 2022). "The same pattern is observed in the studies that measured RBP4 during the third trimester of pregnancy and in studies that investigated severe preeclampsia only." (PMID 36558360, 2022). "In this study, the stratified meta-analysis, based on preeclampsia severity, also indicates that RBP4 is significantly higher in the group with severe preeclampsia only." (PMID 36558360, 2022). "Therefore, further research is needed, which should use a larger sample size, a prospective design and longitudinal sampling for RBP4 to provide better insights into the RBP4 dynamics in preeclampsia cases." (PMID 36558360, 2022). "Perhaps RBP4 is the key modulator for the pathogenesis of both preeclampsia and GDM." (PMID 36558360, 2022). "Likewise, the stratified meta-analysis showed the same pattern in the studies which measured RBP4 levels in the third trimester, as well as in the studies that investigated severe preeclampsia." (PMID 36558360, 2022). "Moreover, RBP4 is found to be positively correlated with systolic blood pressure in severe preeclampsia." (PMID 36558360, 2022). "Since RBP4 is considered a cytokine that can be an inflammatory mediator involved in the pathogenicity of preeclampsia, we hypothesized that its level is expected to be increased among nulliparous women in comparison to multiparous." (PMID 36558360, 2022).
preeclampsia (continued). "Additionally, this list included several genes associated with preeclampsia (PE) such as TIMP3, Wnt regulator DKK1, fibronectin FN1, cannabinoid receptor CNR1, neurokinin receptor TAC3, retinol binding protein RBP4, and prolactin PRL." (PMID 30131724, 2018). "After the retrieval of the articles, 29 were excluded further: 16 studies investigated other adipokines, 11 were found to be irrelevant, one did not mention the measuring unit of RBP4 and one examined preeclampsia in already diabetic patients." (PMID 36558360, 2022). "However, RBP4 is not correlated with the gestational age in normal pregnancy, which may exclude the involvement of adipose tissue as a source of the increment of RBP4 during preeclampsia." (PMID 36558360, 2022).
prostate carcinoma (4 papers, 2013 to 2022). A carcinoma that arises from epithelial cells of the prostate gland. "In the present study, we demonstrated that OPG reduces osteolysis and cancer cell growth in a mouse model of bone metastasis and that expression of RBP4 and PLAC8, which were suggested to be associated with prostate cancer cell growth in vitro, was increased in maintained prostate cancer cells." (PMID 23708710, 2013). "In addition, the expression of RBP4 and PLAC8, which were suggested to be associated with prostate cancer cell growth in vitro, was increased in remaining prostate cancer cells in bone." (PMID 23708710, 2013). "Since the expression of RBP4 and PLAC8 were increased in tumor cells in PC3-GFP/PC3-OPG-injected mice compared to controls, RBP4 and PLAC8 may be acting as survival factors in prostate cancer cells when osteolytic tumor growth is inhibited by OPG." (PMID 23708710, 2013). "RBP4 and PLAC8 may become new therapeutic targets for prostate cancer bone metastasis, to be used in combination with therapies that inhibit the OPG/RANKL/RANK pathway." (PMID 23708710, 2013). "Thus, RBP4 and PLAC8 may become new therapeutic targets for prostate cancer bone metastasis, in combination with OPG/RANKL/RANK pathway inhibition." (PMID 23708710, 2013).
retinal degeneration (4 papers, 2012 to 2025). Degeneration of the retina. "Exome sequencing of three members of a consanguineous pedigree identified a novel homozygous RBP4 mutation in two members with retinal degeneration." (PMID 23189188, 2012). "Of these, only RBP4 was a gene that had been previously reported to be associated with retinal degeneration." (PMID 23189188, 2012). "The retinal degeneration associated with the RBP4 homozygous splice site mutation in our two siblings progressed significantly over a 17-year interval between our examinations in middle age." (PMID 23189188, 2012). "In this study we describe the identification of a novel splice site mutation in the retinal binding protein-4 (RBP4) gene segregating with recessive retinal degeneration in two affected siblings of a consanguineous Caucasian pedigree and the potential implications of the mutation." (PMID 23189188, 2012). "Analysis of RBP4, TTR and levels of retinol in serum further established the effect of c.111+1G>A mutation and its association with the retinal degeneration phenotype observed in this pedigree." (PMID 23189188, 2012). "However, interestingly enough, the Rbp4 knockout mice had a more than 70% reduction in A2E levels and yet a significant inflammatory and oxidative stress response to the point of retinal degeneration." (PMID 40558514, 2025). "Analysis of serum vitamin A levels and serum RPB4 may serve as a cost effective initial screening method in determining the potential involvement of RBP4 in patients with retinal degeneration, specifically those with ocular colobomas." (PMID 23189188, 2012). "These indicate variation in the severity of the retinal degeneration phenotype, developmental abnormalities and non-ocular abnormalities in these two siblings with the RBP4 c.111+1G>A mutation." (PMID 23189188, 2012). "Genetic ablation of Rbp4 in mice does not lead to systemic abnormalities or histological signs of retinal degeneration." (PMID 31978148, 2020). "The reliance of dog on plasma lipoprotein-retinyl ester complexes for vitamin A delivery also indicates that canine models of retinal degeneration may not be used in assessing pre-clinical efficacy of RBP4 antagonists." (PMID 31978148, 2020).
acne (3 papers, 2012 to 2022). An inflammatory process of the sebaceous glands which is characterized by comedones, nodules, papules and/or pustules on the skin. "RBP4 RD was also associated with the presence of developmental abnormalities and severe acne in these patients and may be a hallmark of RBP4 associated RD." (PMID 23189188, 2012). "Our data show that azelaic acid, SELL (Leukocyte-Endothelial Cell Adhesion Molecule 1), APOA1 (Apolipoprotein A1) and RBP4 (Retinol Binding Protein 4) are the drivers of seasonal responses contributing to acne pathophysiology." (PMID 33004787, 2020). "Although the retinal pathology associated with RBP4 mutations is indistinguishable from the recessive RD phenotype due to mutations in other genes, the additional presence of acne or developmental abnormalities is unique to patients with RPB4 associated RD." (PMID 23189188, 2012).
AL amyloidosis (3 papers, 2013 to 2021). AL Amyloidosis is a plasma cell disorder characterized by the aggregation and deposition of insoluble amyloid fibrils derived from misfolding of monoclonal immunoglobulin light chains usually produced by a plasma cell tumor. "Using 2-DE, a change (decrease) in RBP4 was also observed in the group of chemosensitive patients with multiple myeloma, which were treated with bortezomib-based regimens, when compared with patients resistant to chemotherapy, and also in the sera of epithelial ovarian cancer patients." (PMID 23566303, 2013). "Urinary retinol binding protein 4 (uRBP), a low molecular weight tubular protein and highly sensitive marker of PTD, was prospectively measured in 285 newly diagnosed, untreated patients with systemic AL amyloidosis between August 2017 to August 2018." (PMID 34374069, 2021). "Unlike AL amyloidosis, there are no specific circulating biomarkers of ATTR-CA, although the endogenous transthyretin ligand retinol binding protein-4 (RBP4) has shown promising results." (PMID 34575344, 2021).
alcohol (3 papers, 2019 to 2025). "Based on these findings, Rbp4, which demonstrated a significant linear correlation with lipid accumulation, was ultimately selected as the primary research target to further investigate its molecular regulatory mechanisms in alcohol-induced liver injury." (PMID 40442809, 2025). "Sil increased the levels of RBP4 and reduced the levels of IL-7, YKL 40, and PAI-1 in the liver (p < 0.05), but only reduced the levels of YKL 40 and PAI-1 in the serum of mice with alcohol-induced acute liver injury (p < 0.05)." (PMID 31396303, 2019). "ACT and Sil failed to affect the hepatic levels of TPO, RBP4, IL-23, ICAM-1, NGAL, and VCAM-1 in acute alcohol-injured mice compared with the model group." (PMID 32719658, 2020).
Anxiety (3 papers, 2024 to 2025). Intense feelings of nervousness, tension, or panic often arise in response to interpersonal stresses. "While the precise function of RBP4 in the central nervous system remains unclear, studies have shown that RBP4-deficient mice display decreased mobility and anxiety-like behavior, along with neuronal loss and gliosis in the cerebral cortex and hippocampus." (PMID 39170638, 2024). "Hepatomegaly was observed in Rbp4:Cre; MEK1S217/221E mice, and mouse models of chronic liver disease have been shown to exhibit hypo-locomotion in the open-field test, but they show little change in motor learning or anxiety-like phenotypes." (PMID 38826084, 2024).
asthma (3 papers, 2023 to 2024). "In asthma, decreased RBP4 expression is associated with increased inflammation." (PMID 38018577, 2023).
autism (3 papers, 2021 to 2025). Persistent deficits in social interaction and communication and interaction as well as a markedly restricted repertoire of activity and interest as well as repetitive patterns of behavior. "In this context, recent evidence in a mouse model showed that embryonic Rbp4-Cre neurons strongly express autism-associated genes, and perturbing these genes interferes with the switch between the two motifs." (PMID 39061976, 2024). "Furthermore, the levels of RBP4 were positively correlated with TG and were negatively correlated with the severity of autism." (PMID 34446012, 2021). "Retinol-binding protein 4 (RBP4) is hypothesized to function as an inflammatory neurotrophic adipokine capable of crossing the blood-brain barrier, which is frequently compromised in many individuals with autism." (PMID 40998031, 2025).
breast tumors (3 papers, 2008 to 2020). "IH data were available for CDH1, TFAP2A, and RBP4 proteins; and only data from antibodies exhibiting differential expression among breast tumors were reported herein." (PMID 19116033, 2008). "The RBP4 protein may be an important driver of metastasis and angiogenesis of breast tumors." (PMID 32156052, 2020).
cognitive decline (3 papers, 2020 to 2024). "Indeed, this decrease is associated with cognitive decline, suggesting that RBP4 might be a biomarker for AD progression." (PMID 32518535, 2020). "In contrast, a previous study showed that RBP4 is not correlated with the incidence or cognitive decline of dementia." (PMID 37808505, 2023).
cyst (3 papers, 2019 to 2023). A sac-like closed membranous structure that may be empty or contain fluid or amorphous material. "At 106-108 h PHS, more than half of wild-type time-course testes contained at least one cyst showing meiotic entry, whereas lut and rbp4 mutants hit that benchmark at 98-100 h PHS and 100-102 h PHS, respectively." (PMID 37882771, 2023). "In contrast to controls, a significantly higher percentage of testes in which Par complex function had been knocked down in cyst cells showed LysoTracker staining among germ cells that express the early spermatocyte marker Rbp4 (quantified in E)." (PMID 30918053, 2019). "Importantly, Rbp4-Gal4-driven GFPnls signal was undetectable in somatic cyst-cell nuclei (outlines), indicating that Rbp4-Gal4 activity is restricted in the testis to the germline." (PMID 37436409, 2023). "Appearance of cysts of round spermatids ran about 6 h earlier in both lut and rbp4 mutants compared with wild-type testes, as about one-third of testes from those two mutant genotypes contained at least one cyst with round spermatids at 104-106 h PHS (versus 110-112 h PHS in wild type)." (PMID 37882771, 2023).
depression (3 papers, 2021 to 2025). "Former studies have found that Serum RBP4 levels of major depressive depression individuals were significantly lower than that of the healthy control group." (PMID 34446012, 2021). "Similar to our findings, Qian Yao used the 24-item Hamilton Depression Scale to see if serum retinol-binding protein 4 (RBP4) concentrations may change depression symptoms in individuals." (PMID 35845773, 2022). "And the level of RBP4 in patients with major depressive depression (MDD) was lower than normal people." (PMID 35845773, 2022).
hemorrhagic stroke (3 papers, 2022 to 2024). A stroke caused by a bleed on the brain. "Retinol binding protein 4 (RBP4) is linked to the severity of cardiovascular disorders, and complement factors are known to be associated with hemorrhagic stroke." (PMID 38731959, 2024).
hypervitaminosis A (3 papers, 2012 to 2015). A symptom complex resulting from ingesting excessive amounts of vitamin A. "The result clearly predicts that significant downregulation of RBP4 can cause hypervitaminosis A and hyperretinoic acidosis, which probably may result in a certain degree of teratogenicity." (PMID 23028466, 2012). "In an experimental study, it was suggested that prenatal exposure to valproate may down-regulate retinol binding protein-4, which induces hypervitaminosis A." (PMID 24416231, 2014).
pulmonary TB (3 papers, 2012 to 2026). "Notably, RBP4 levels are markedly reduced in whole‐blood supernatants of patients with active pulmonary TB." (PMID 41477556, 2026). "We have recently conducted a proteomic research and demonstrated that plasma levels of fetuin-A and retinol-binding protein 4 (RBP4), also closely linked to the metabolic and inflammatory state, were significantly lower in patients with active pulmonary TB than in control subjects." (PMID 22685600, 2012).
viral infection (3 papers, 2020 to 2025). "To ascertain whether the attenuated virus infection in RBP4-deficient cells was due to lower levels of CD36, we investigated the impact of SA expression in these cells through CD36 overexpression." (PMID 41144502, 2025). "Here, we found that RBP4 facilitates IAV infection by modulating cellular cholesterol homeostasis, adding a mechanism by which RBP4 promotes virus infection." (PMID 41144502, 2025). "Overall, our findings identify RBP4 as a critical host factor that regulates influenza virus infection and uncover a previously unrecognized function of RBP4 in facilitating virus infection through the modulation of cholesterol metabolism." (PMID 41144502, 2025). "How RBP4 levels evolved had been studied in other viral infections, particularly human immunodeficiency virus (HIV), given that lipodystrophy was frequently recognized among people living with HIV receiving combination antiretroviral therapy." (PMID 33135589, 2020). "Notably, recent studies have shown strong correlations between RBP4 levels and infection by multiple viruses, yet the exact roles of RBP4 in virus infection remain unclear." (PMID 41144502, 2025).
adenoma (2 papers, 2017 to 2020). A neoplasm arising from the epithelium. "Two panels, one consisting of Hp and LRG1 and one of Hp, LRG1, RBP4, and FN1, were identified for high‐risk adenomas and CRCs detection (sensitivity of 66% and 62%, respectively, at specificity of 95%)." (PMID 31784980, 2020). "We identified a biomarker panel of Hp, LAMP1, SYNE2, and ANXA6 for identification of high‐risk adenomas and two biomarker panels – Hp and LRG1, as well as Hp, LRG1, RBP4, and FN1 – for identification of high‐risk adenomas and CRCs that outperformed hemoglobin." (PMID 31784980, 2020). "Next to Hp, LAMP1, SYNE2, and ANXA6 were selected in the analysis for high‐risk adenomas, and also LRG1, RBP4, and FN1 for the high‐risk adenomas and CRCs." (PMID 31784980, 2020). "We conclude that Hp, LAMP1, SYNE2, LRG1, RBP4, FN1, and ANXA6 may be of value as stool biomarkers for early detection of high‐risk adenomas and CRCs." (PMID 31784980, 2020). "So we think if the authors could analyze the correlationship of serum RBP4 in each adenoma subgroup, the results are more meaningful." (PMID 29190912, 2017).
anemia (2 papers, 2013 to 2025). A reduction in the number of red blood cells, the amount of hemoglobin, and/or the volume of packed red blood cells. "Further, agreement in 2D electrophoresis results for retinol-binding protein 4 was observed when compared to our previous study of refractory anemia with excess blasts subtype 1." (PMID 23566303, 2013).
Atrophy (2 papers, 2022 to 2024). Any weakening or degeneration, especially through lack of use. "To evaluate the possible involvement of RBP4 in the pathogenesis of muscle atrophy, we first examined RBP4 expression in the skeletal muscles of mice suffered from denervation." (PMID 39031684, 2024).
Cognitive impairment (2 papers, 2020 to 2023). Abnormal cognition is characterized by deficits in thinking, reasoning, or remembering. "Particularly intriguing is the correlation of decreasing RBP4 in the CSF with progression of normal to mild cognitive impairment to AD, suggesting a movement of RBP4 between brain compartments with disease, although this study was with a small patient pool." (PMID 31884477, 2020).